PPARA (peroxisome proliferator activated receptor alpha)
Diseases named in the same sentence as PPARA in open-access papers (continued):
Sharing a sentence is not in itself a finding about the gene and the disease.
non-alcoholic fatty liver disease (136 papers, 2011 to 2026). "In patients with non-alcoholic fatty liver disease, circRNA_0046367 can regulate liver steatosis and oxidative stress through the circRNA_0046367/miR-34a/PPARα pathway, thereby improving hepatotoxicity caused by lipid peroxidation." (PMID 37957626, 2023). "Elafibranor and GFT505, which act as dual PPARα and PPARδ agonists, have shown a good response in the treatment of non-alcoholic steatohepatitis/non-alcoholic fatty liver disease (NASH/NAFLD) and its associated metabolic syndrome (MetS)." (PMID 34639224, 2021). "Two recent studies suggested that DEHP may cause lipid accumulation and nonalcoholic fatty liver disease (NAFLD) by promoting PPARα and sterol regulator element-binding protein 1c (SREBP-1c) expression." (PMID 29391432, 2018). "PPARA is related to nonalcoholic fatty liver disease because deficiency in PPARA leads to lipid accumulation in the liver and researchers have proposed up‐regulation of its activity may be an effective treatment for nonalcoholic fatty liver disease." (PMID 32684953, 2020). "TET1 was found to bind directly to the promoter of PPARα and increase its hydroxymethylation level, ultimately inhibiting the progression of non-alcoholic fatty liver disease." (PMID 40520993, 2025). "Previous studies have established that curcumin can inhibit the activity of DNMT in non‐alcoholic fatty liver disease, reducing the PPARα promoter methylation and subsequent hepatocyte apoptosis." (PMID 40909259, 2025). "Wang et al108 found that TET1 played a protective role against non-alcoholic fatty liver disease by promoting fatty acid oxidation through the activation of the peroxisome proliferator-activated receptor alpha (PPARα) pathway." (PMID 40520993, 2025). "The promoter of PPARA is hypermethylated in type 2 diabetic patients with non-alcoholic fatty liver disease (NAFLD)." (PMID 39595621, 2024). "The non-alcoholic fatty liver disease showed a transcriptional alteration in the Fas, Pparα, and Tnf genes, consistent with literature where similar changes induced by HDF were observed." (PMID 39766314, 2024). "For instance, hepatic adenosine kinase overexpression elevated DNA methylation and reduced PPARα expression, leading to increased fatty acid oxidation and inflammation in non-alcoholic fatty liver disease." (PMID 36866528, 2023). "Decitabine increases the expression of PPARα (Peroxisome proliferator activated receptor alpha) mRNA by regulating DNA methylation levels and reducing lipid accumulation, thereby alleviating non-alcoholic fatty liver disease." (PMID 37626900, 2023). "Maternal high-fat diet decreased the expression of PPARα and genes for fatty acid oxidation, which contributes to nonalcoholic fatty liver disease (NAFLD) in offspring." (PMID 36359869, 2022). "TET1 has been reported to inhibit the progression of nonalcoholic fatty liver disease by hydroxymethylation of the PPARα promoter." (PMID 36195596, 2022). "Li and the group reported analogs of benzimidazole scaffold as a dual agonist of PPARα/δ for the treatment of non-alcoholic fatty liver disease." (PMID 36297575, 2022). "Meanwhile, curcumin improved lipid accumulation in nonalcoholic fatty liver disease via increasing PPARα mRNA and protein levels in the liver and inhibition of DNA methylation at the PPARα gene." (PMID 36092543, 2022). "It has been reported that PPARα can affect the development of nonalcoholic fatty liver disease (NAFLD) and nonalcoholic steatohepatitis (NASH)." (PMID 31336903, 2019). "More recently, pharmacological targeting of PPARα has shown promise for the treatment of non-alcoholic fatty liver disease." (PMID 26449539, 2015). "Cd36, Cidea, and Fabp1 are considered PPARA-dependent genes that are highly expressed under metabolic stress in liver and could be potential therapeutic targets for nonalcoholic fatty liver disease." (PMID 38786053, 2024).
non-alcoholic fatty liver disease (continued). "We investigated whether fenofibrate can reduce visceral obesity and nonalcoholic fatty liver disease via adipose tissue PPARα activation in female ovariectomized (OVX) C57BL/6J mice fed a high-fat diet (HFD), a mouse model of obese postmenopausal women." (PMID 33916086, 2021). "We have recently shown that bilirubin has a hormonal function by binding directly to PPARα, inducing transcriptional activity of genes involved in hepatic glycogen synthesis and β-oxidation in models of dietary-induced non-alcoholic fatty liver disease (NAFLD)." (PMID 32961782, 2020). "Clinical trials are evaluating PPARα activation for treating non-alcoholic fatty liver disease and primary biliary cirrhosis, in combination with existing treatments (ClinicalTrials.gov identifier: NCT00262964, NCT00575042, NCT02823353, NCT02965911, NCT02823366)." (PMID 30486822, 2018). "In addition, PPARα ligands and dual PPARα/PPARδ ligands are being explored for the treatment of non-alcoholic fatty liver disease." (PMID 25511156, 2014). "Fenofibrate communicates with PPARα, activates PPARα related signaling pathways mediate adipocyte proliferation, regulates body fat metabolism, facilitates fat redistribution, avoids excessive accumulation of liver fat, and improves non-alcoholic fatty liver disease." (PMID 38173037, 2024). "Peroxisome proliferator-activated receptors (PPARs) are crucial in the pathogenesis of non-alcoholic fatty liver disease (NAFLD), PPARα primarily enhances fatty acid oxidation in the liver, while PPARG (PPARγ) facilitates lipid transport." (PMID 40176148, 2025). "In non-alcoholic fatty liver disease (NAFLD), lncRNA-MALAT1 regulates hepatic lipid accumulation mediated by PPARα/CD36 through the miR-206/ARNT axis, positively correlating with the severity of NAFLD." (PMID 39044218, 2024). "Peroxisome proliferator-activated receptor alpha (PPARα) and carnitine palmitoyltransferase 1 (CPT1) are important targets of lipid metabolism regulation for nonalcoholic fatty liver disease (NAFLD) therapy." (PMID 38202597, 2023). "Numerous researches have demonstrated that PPARα negatively affects the proinflammatory and Acute Phase Reaction (APR) signaling pathways, as observed in the Systemic Inflammatory, Atherogenic, and Nonalcoholic Fatty Liver Disease (NASH) models." (PMID 37780625, 2023). "Here, the authors show hyodeoxycholic acid (HDCA) ameliorates nonalcoholic fatty liver disease by inhibiting the formation of RAN/CRM1/PPARα nuclear export heterotrimer, resulting in increased nuclear localization of PPARα and activated fatty acid oxidation." (PMID 37673856, 2023). "Downregulation of miR-34a potentially contributes to altered lipid metabolism in nonalcoholic fatty liver disease (NAFLD) by regulating its targets, PPARα and SIRT1." (PMID 36611960, 2022). "In mice, Cyp4A14 expression has been shown to be induced by PPARα and to be increased in HFD-induced nonalcoholic fatty liver disease." (PMID 34488621, 2021). "Emodin (0.25 or 0.5 μg/ml) was reported to attenuate nonalcoholic fatty liver disease (NAFLD) in zebrafish by activating AMPK pathway, via improving PI3K/AKT2/AMPKα-mediated IR and enhancing AMPKα/PPARα/CPT1 and AMPKα/PPARα/ACOX1-mediated fatty acid oxidation." (PMID 34629100, 2021). "Despite the lack of direct evidence that GA upregulates FAO-related enzymes in the kidney, studies using a hepatocellular model of non-alcoholic fatty liver disease (NAFLD) have shown that GA increases the expression of FAO-related genes, such as PPARα and CPT1A, thereby reducing hepatic steatosis." (PMID 41170356, 2025). "For example, In a rat model of non-alcoholic fatty liver disease (NAFLD), curcumin treatment significantly reversed DNA methylation levels, increased expression of peroxisome proliferator activated receptor alpha (PPAR -α) and protein, and improved lipid accumulation in the model." (PMID 36712965, 2022).
non-alcoholic fatty liver disease (continued). "Specifically, the dual PPARα/δ agonist GFT505 was shown to improve liver dysfunction markers, decrease hepatic lipid accumulation, and reduce inflammatory gene expression in liver in several animal models of non-alcoholic fatty liver disease (NAFLD)." (PMID 26449539, 2015). "Moreover, the effect of chlorogenic acid on expression of hepatic peroxisome proliferator-activated receptor-alpha and on activation of 5′ AMP-activated protein kinase partly explain the presumed liver protective effect of coffee from non-alcoholic fatty liver disease." (PMID 25886384, 2015).
cardiac hypertrophy (118 papers, 2009 to 2025). "Noteworthy in vitro and in vivo models of cardiac hypertrophy showed a decreased expression of the gene encoding for PPARα (PPARA) and reduced biochemical activity." (PMID 41008965, 2025). "The deficiency of Plin5 exacerbates the progression of cardiac hypertrophy and heart failure induced by pressure overload, concurrently reducing cardiac lipid accumulation and upregulating the levels of PPARα and PGC-1α." (PMID 40166465, 2025). "PPARα overexpression significantly alleviated PO‐induced cardiac hypertrophy and dysfunction in mice with Lgr6 deficiency." (PMID 40211903, 2025). "Pellieux and colleagues have demonstrated that overexpression of angiotensinogen in the heart induced maladaptive cardiac hypertrophy, associated with reduction of PPARα and enzymes of fatty acid metabolism, while glucose oxidation was unchanged." (PMID 38397106, 2024). "Cardiac specific overexpression of PPARα elevates fatty acid oxidation and cardiac lipid accumulation, inducing cardiac dysfunction and increasing susceptibility to cardiac hypertrophy." (PMID 35259201, 2022). "The increase in fatty acid oxidation in the diabetic heart is associated with an increase in PPARα, which plays a key role in the development of cardiac hypertrophy and dysfunction in DCM." (PMID 34122133, 2021). "On the other hand, overexpression of PPARα increased mild cardiac hypertrophy, ventricular dysfunction, and lipotoxicity associated with reciprocal repression of glucose uptake and oxidation in the mouse heart." (PMID 30400386, 2018). "PPARα downregulation is observed in cardiac hypertrophy and heart failure, suggesting that PPARα deficiency can impair heart functional capacity." (PMID 27807394, 2016). "Fenofibrate, a PPARα activator, has been reported to reduce ET-1-caused cardiac hypertrophy through downregulation of activating protein-1 (AP-1) binding and inhibition of p38 mitogen-activated protein kinases (MAPK) signaling." (PMID 27807394, 2016). "In agreement with what is described for other models of cardiac hypertrophy, we observed a tendency towards a decrease in PGC1α/β and in PPARα mRNAs caused by HFD in WT mice." (PMID 27832814, 2016). "Moreover, miR-34a, miR-132, and miR-331 were downregulated, implicating a miRNA-mediated mechanism in PPARα-linked cardiac hypertrophy." (PMID 41008965, 2025). "Not only antiatherogenic and anti-inflammatory actions of statins have been associated with the activation of PPARα and γ (, but also cardioprotective statin effects, such as the inhibition of cardiac hypertrophy and fibrosis, can be attributed to PPARα and γ modulation." (PMID 36768666, 2023). "Furthermore, PPARα-deficient mice are more prone to cardiac hypertrophy in response to pressure overload." (PMID 35479323, 2022). "In addition, there is a causal relationship between the production of ROS and the downregulation of PPARα in myocardial hypertrophy caused by hypertension, and this ultimately leads to myocardial energy impairment." (PMID 33132907, 2020). "Moreover, decreased expression of PPARα has been reported to be associated with the development of pathological cardiac hypertrophy, and abnormalities in metabolism have been shown to be involved in that process." (PMID 29339422, 2019). "Likewise, fenofibrate treatment increased cardiac hypertrophy and fibrosis along with a decrease in fractional shortening during pressure overload in PPARα deficient mice." (PMID 30111698, 2018). "Peroxisome proliferator-activated receptor α (PPARα) plays a role in the pathogenesis of cardiac hypertrophy, although its underlying mechanism remains unclear." (PMID 27807394, 2016). "In addition to PPARγ, in mouse models of cardiac hypertrophy and heart failure, the activation of PPARα has also been shown to cause noxious effects on the development of the ventricular function." (PMID 19173749, 2009).
cardiac hypertrophy (continued). "The transcription factor peroxisome proliferator-activated receptor alpha (PPARα) regulates genes involved in fatty acid oxidation and a down-regulation of PPARα is associated with reduced fatty acid oxidation and a transition to heart failure in pressure-overload-induced cardiac hypertrophy." (PMID 35325070, 2023). "Interestingly, when cardiomyocytes-specific PPARγ-overexpressing mice were crossed with PPARα-deficient mice, cardiac hypertrophy was significantly ameliorated, along with upregulated FAO and decreased apoptosis, reactive oxygen species (ROS) levels, and endoplasmic reticulum stress." (PMID 35185581, 2022). "In age-related myocardial hypertrophy and myocardial hypertrophy caused by pressure overload, increased ceramide levels can be observed, which may be due to the inhibition of peroxisome proliferator-activated receptor alpha (PPARα)." (PMID 35111371, 2022). "However, whole body PPARα knockout mice are also more susceptible to cardiac lipid accumulation and there are inconsistent reports on the susceptibility of these mice to developing cardiac hypertrophy." (PMID 35259201, 2022). "In addition, PPARα can ameliorate cardiac hypertrophy caused by hypertension." (PMID 35097008, 2021). "We thus generated an in vitro model of cardiac hypertrophy by stable silencing of the PPARA gene in H9c2 rat cardiomyoblasts." (PMID 41008965, 2025). "Overexpressing PPARα and USP4 mitigated the exacerbation of PO‐induced cardiac hypertrophy and dysfunction caused by Lgr6 deficiency." (PMID 40211903, 2025). "For example, overexpression of MIAT exacerbates cardiac hypertrophy via the PPARα/CPT-1a signaling pathway." (PMID 40290189, 2025). "Studies have shown that baicalin induces PPARα and PPARβ/δ expression, attenuates pressure overload-induced cardiac hypertrophy, and inhibits ventricular remodeling in both mouse models and H9C2 cells." (PMID 39185317, 2024). "Downregulation of PPARα activity and expression during cardiac hypertrophy inhibits CPT-1 expression, which reduces the ability of the myocardium to maintain energy metabolic homeostasis." (PMID 39185317, 2024). "In contrast, PPARα agonists prevent myocardial mitochondrial damage and ameliorate cardiac hypertrophy." (PMID 39185317, 2024). "Xieet al. reported that USP28 regulates mitochondrial homeostasis via the PPARα-Mfn2 axis and modulates cardiac hypertrophy in diabetic cardiomyopathy." (PMID 39210825, 2024). "The SIRT1:PPARα interaction was protective in cardiac hypertrophy and the deregulation of its related signaling pathway was associated with reduced fatty acid oxidation in the liver." (PMID 38534754, 2024). "Previous studies have shown that PPARα has a negative regulatory role in the development of pathological cardiac hypertrophy." (PMID 39185317, 2024). "PPARα plays an important role in cardiac metabolism and anti-inflammation, which is considered to be important in cardiac hypertrophy and fibrosis." (PMID 37221368, 2023). "PPARα knockout mice are protected from the severe cardiomyopathic phenotype in diabetes-induced cardiac hypertrophy." (PMID 37233656, 2023). "In contrast, pressure overload-induced cardiac hypertrophy has reduced MCD activity owing to PPARα inhibition." (PMID 37233656, 2023). "Cardiomyocyte specific ATGL knockout resulted in cardiac hypertrophy and heart failure in mice, which was derived from PPARα dysfunction." (PMID 35479323, 2022). "Nevertheless, the downregulation of PPARα expression is common in cardiac hypertrophy, and PPARα knockdown worsen cardiac hypertrophy, suggesting that PPARα dysfunction played an important role of PPARα in the development of cardiac hypertrophy." (PMID 35479323, 2022).